ICAM1 (intercellular adhesion molecule 1)
Diseases named in the same sentence as ICAM1 in open-access papers (continued):
Sharing a sentence is not in itself a finding about the gene and the disease.
diabetes (continued). "Intravitreal injection of HMGB1 mimics the effects of diabetes and increases RAGE, ERK1/2, NF-κB, and proinflammatory biomarkers such as ICAM-1 and soluble ICAM-1." (PMID 32722545, 2020). "In a rat model of STZ-induced diabetes, intravitreal injections of α-MSH reduced oxidative stress, inflammation, and apoptosis, while they also inhibited the expression of ICAM-1, indicating reduced leukostasis." (PMID 31787868, 2019). "The gradual increase in the levels of TGF-β1, ICAM-1, and phospho-p38, with a concurrent time-dependent decrease in SMAD7 levels, suggested that diabetes-induced fibrotic changes began at 8 wk postinduction." (PMID 30093732, 2018). "Our study shows that PA significantly reduces ROS overproduction and eventually inhibits the expressions of FN and ICAM-1 in both HG-induced GMCs and STZ-induced diabetic mice." (PMID 29867511, 2018). "In earlier studies, ICAM-1 predicted presence of coronary artery calcification (other CAMs were not studied), and only ICAM-1 and E-selectin predicted future diabetes." (PMID 28596958, 2017). "Studies have shown that lutein can attenuate oxidative stress in experimental models of early DR and zeaxanthin significantly inhibits diabetes-induced retinal oxidative damage and elevations in VEGF and adhesion molecule ICAM-1 in diabetic rats." (PMID 29046877, 2017). "In our results, ICAM-1, MCP-1, and FKN mRNA levels were significantly elevated in the retinas of the Diabetes group compared with the healthy Control group." (PMID 26765843, 2016). "ICAM-1 and FKN levels were significantly lower in AST Low group than in the Diabetes group (p < 0.05)." (PMID 26765843, 2016). "Diabetes and hyperglycemia also lead to increased expression of E-selectin, VCAM-1, and ICAM-1 by endothelial cells." (PMID 26539228, 2015). "In one of the study the authors found a positive association between air pollution and inflammatory markers as ICAM-1, VCAM-1 and vWF, suggesting that inflammatory mechanisms may explain the increased risk of air pollution-associated cardiovascular events among persons with diabetes." (PMID 24886318, 2014). "To determine the role of TLR2 and 4 in the pathogenesis of microangiopathy, we assessed for ICAM-1 expression in TLR2-/- and TLR4-/- murine models after the induction of diabetes." (PMID 25303153, 2014). "After 4 weeks of diabetes, early signs of retinopathy were examined by measuring ROS, expression of VEGF and ICAM-1, leukocyte attachment to the vessel wall and vascular permeability." (PMID 24358357, 2013). "Diabetes-induced increases in leukostasis and breakdown of the blood-retinal barrier have been shown to be mediated by increases in VEGF and ICAM1 expression." (PMID 24358357, 2013). "The diabetes-induced increases in both VEGF and ICAM1 were markedly attenuated in the NOX2-/-→WT and WT→NOX2-/- chimeras." (PMID 24358357, 2013). "After 12 weeks of diabetes, renal protein and mRNA MCP-1 and ICAM-1 expression, and levels of TNF-α and IL-6, were markedly increased in the DM group, as compared with NC rats." (PMID 23935673, 2013). "Previously, it was shown that 1 week after diabetes was induced, the retinal ERK1/2, vascular endothelial growth factor (VEGF), ICAM-1, leukostasis, and retinal vascular permeability are significantly upregulated." (PMID 23671886, 2013). "First, deletion of proteins mediating leukocyte adhesion, ICAM1 or its binding partner on leukocytes integrin subunit β2 (CD18), significantly inhibited the diabetes-induced vascular permeability and degeneration of retinal capillaries in animals." (PMID 24205223, 2013). "Deletion of MyD88 from only marrow-derived cells totally inhibited the endothelial ICAM-1 induction in retinas from diabetic animals, and signaling through both TLR2/4 and IL-1β contributed partially to altered regulation of ICAM-1 in diabetes." (PMID 23874797, 2013).
diabetes (continued). "These diabetes-induced alterations were correlated with increases in expression of VEGF and ICAM-1, leukocyte adhesion and vascular permeability." (PMID 24358357, 2013). "We therefore used western blotting to determine the effects of diabetes on levels VEGF and ICAM1 in the NOX2 chimeras." (PMID 24358357, 2013). "Not only ICAM-1 but also LFA-1 (CD11a/CD18) and Mac-1 (CD11b/CD18) ligands for ICAM-1 are upregulated in patients with diabetes." (PMID 22132315, 2012). "Therefore, ICAM1 may play a role in the development of diabetes and diabetic nephropathy." (PMID 23346076, 2012). "The authors found that cloricromene significantly lowered retinal TNF-α, ICAM-1, VEGF, and nitric oxide synthase (eNOS) levels and suppressed diabetes-related BRB breakdown by 45%." (PMID 23028203, 2012). "Immunohistochemistry studies reported constitutive low-level expression of ICAM-1 in the normal retina and upregulation of ICAM-1 in the retinal vasculature of patients with diabetes." (PMID 19626134, 2009). "Intraperitonealadministration of telmisartan inhibited diabetes and glucose-induced retinalexpression of ICAM-1 and VEGF, and upregulation of ICAM-1 and MCP-1, viainhibition of nuclear translocation of NF-κB." (PMID 18509499, 2008). "In addition, the serum levels of intercellular adhesion molecule-1 (ICAM-1) and vascular adhesion molecule-1 (VCAM-1) also show significant differences between DR and diabetes, and gradually increase as DR progresses to PDR." (PMID 40564025, 2025). "In contrast to the heart, diabetes did not affect the numbers of ICAM‐1+ or VCAM‐1+ blood vessels in the brain." (PMID 35488737, 2022). "Indeed, administration of resveratrol to diabetes murine models considerably reduced retinal leukocyte adhesion induced by diabetes and decreased the retinal expression of VEGF and ICAM-1." (PMID 35409409, 2022). "For example, knockout or suppressing ICAM-1 considerably reduced retinal leukocyte infiltration and vascular leakage in diabetic mice, whereas MCP-1 knockout animals exhibited significantly reduced retinal vasculopathy following diabetes induction." (PMID 35802672, 2022). "To test this hypothesis, we looked at the level of downstream inflammatory proteins, ICAM-1 and iNOS in the RPE after 2 months of diabetes." (PMID 36229454, 2022). "Increased Intercellular Adhesion Molecule 1 (ICAM-1) and P- selectin immunoreactivity in the diabetic choroidal vessels compared to subjects with no diabetes were already shown." (PMID 34980024, 2022). "Positive immunostaining was observed for ICAM-1 and MCP-1 in the retina of patients with diabetes." (PMID 34281287, 2021). "Cumulative evidence suggests that the upregulation of inflammatory factors such as tumor necrosis factor-α (TNF-α), intercellular adhesion molecule-1 (ICAM-1) and monocyte chemoattractant factor-1 (MCP-1 or CCL2), and subsequent leukocyte diapedesis, contribute to the BRB breakdown in diabetes." (PMID 34200613, 2021). "Accumulating evidence suggests that DR exhibits characteristics of chronic inflammation, as multiple pro-inflammatory factors such as tumor necrosis factor-α (TNF-α), intercellular cell adhesion molecule-1 (ICAM-1), and VEGF are overexpressed in the diabetic retina." (PMID 33291567, 2020). "In this study, we showed that STZ-induced diabetes resulted in DR, and 12 weeks of LTF treatment ameliorated retinal damage, delayed DR occurrence, and significantly decreased the expression of TNF-α, IL-1β, MCP-1, and ICAM-1." (PMID 31956338, 2020). "The CAPN1ΔPF4 mice were also protected from diabetes-induced vascular inflammation as while STZ-treatment resulted in a decrease in PAR-1 and an increase in ICAM-1 expression in aortic endothelial cells from wild-type mice no such changes were observed in aortae from mice lacking platelet CAPN1." (PMID 33258989, 2020).
diabetes (continued). "The overexpression of adhesion molecules (such as ICAM-1, VCAM-1, ninjurin-1) on EC plasma membrane stimulates monocytes adhesion and transmigration into the subendothelial space, contributing to atherosclerosis initiation and progression in diabetes." (PMID 33375461, 2020). "ICAM-1 and/or VCAM-1 have a good correlation with cardiovascular disease in patients with diabetes." (PMID 32509150, 2020). "ICAM-1 gene deletion or the use of an anti-ICAM-1 antibody reduced macrophage infiltrate as well as decreased mesangial proliferation, glomerular Col IV expression and albuminuria in different experimental models of diabetes." (PMID 32471207, 2020). "Indeed, in retinas of STZ rats, zeaxantin inhibited the diabetes-induced oxidative stress as well as the upregulation of VEGF and intercellular adhesion molecule-1 (ICAM-1), an indicator of leukocyte adhesion." (PMID 31787868, 2019). "Indeed, in diabetic rat retinas, DNMT inhibition restored antioxidant enzyme expression and, in parallel, also prevented the diabetes-induced increase of VEGF and of ICAM-1 expression." (PMID 31787868, 2019). "There were several studies have described the increased levels of circulating soluble E-selectin in patients with diabetes, obesity, and coronary artery disease, and soluble VCAM-1 and/or soluble ICAM-1 are increased in patients with metabolic syndrome who involve both male and female." (PMID 31550292, 2019). "Indeed, an ETRA antagonist has been reported to block the diabetes-induced upregulation of both VEGF and ICAM-1 in retinas of STZ rats, while other observations have described positive effects of ETR inhibition on both neuronal and vascular changes seen in DR." (PMID 31787868, 2019). "This suggests that miR-200a/200b mimics may play a therapeutic role by decreasing diabetes-induced endothelial inflammation through the downregulation of both OGT and ICAM-1." (PMID 29720943, 2018). "Moreover, it has been demonstrated, that photoreceptors themselves produce inflammatory cytokines such as ICAM-1, COX-2 and iNOS in experimental diabetes." (PMID 29565290, 2018). "Diabetes-induced increases in ROS production, vascular endothelial growth factor (VEGF) and intercellular adhesion molecule 1 (ICAM1) expression, leukocyte adhesion to the retinal vessels, and breakdown of the blood-retinal barrier were all prevented by deletion of the NADPH oxidase 2 (NOX2) gene." (PMID 28617308, 2017). "We measured several plasma biomarkers of endothelial cell activation (soluble E-selectin, soluble ICAM-1 and fractalkine) and barrier function (angiopoietin-1 and angiopoietin-2), neither of which was modified in patients with diabetes mellitus." (PMID 27495247, 2016). "Quantitation of the relative band intensities showed that the retinas from the AST High group contained significantly lower levels of all three inflammatory proteins than the Diabetes group (p < 0.05), and MCP-1 and ICAM-1 expression were also reduced in the AST Low group (p < 0.05)." (PMID 26765843, 2016). "In the present study, a significantly increased concentration of ICAM-1 and VEGF in the diabetic rats probably suggests that the inflammatory processes may contribute to the development of diabetes mellitus." (PMID 27042190, 2016). "Müller cells when injured in diabetes exhibit a pro-inflammatory phenotype reflected by increased expression of MCP-1, which acts to attract microglia to the retina, and leukocyte adhesion molecules such as ICAM-1." (PMID 26222724, 2015). "In contrast, inhibition of HO-1 did not counteract the effect of PBM on the diabetes-induced generation of superoxide or expression of ICAM-1, iNOS or HO-1." (PMID 26426815, 2015). "In Müller cells, FT011 reduced diabetes-induced gliosis and vascular endothelial growth factor (VEGF) immunolabeling and the hyperglycaemic-induced increase in ICAM-1, monocyte chemoattractant protein-1, CCL20, cytokine-induced neutrophil chemoattractant-1, VEGF and IL-6." (PMID 26222724, 2015).
diabetes (continued). "Moreover, we have uniquely shown that there is a marked reduction in glomerular ICAM-1 expression in TLR2-/- and TLR4-/- murine models compared to wildtype mice induced with diabetes." (PMID 25303153, 2014). "Although the increased expression of ICAM-1 is not exclusive of diabetes, a linkage of the ICAM-1 gene to diabetes and diabetic nephropathy suggests a selective involvement of this particular inflammatory event in both type 1 and type 2 diabetes." (PMID 25126086, 2014). "Multiple exposures of control mice to 50 mGy had no impact on renal ICAM-1 levels but significantly attenuated diabetes-induced ICAM-1 levels after treatment for 4 weeks." (PMID 24651118, 2014). "In our laboratory, we recently demonstrated that diabetes induced significant upregulation of retinal expression of HMGB1, RAGE, activated NF-κB, activated ERK1/2, and ICAM-1 and that intravitreal administration of HMGB1 in normal rats mimics the effect of diabetes." (PMID 24733965, 2014). "Expression of iNOS and ICAM-1 in whole retina were significantly increased by diabetes compared to that of wildtype nondiabetic animals (both p<0.05), but deletion of AR inhibited the diabetes-induced enzyme induction only for iNOS." (PMID 23614016, 2013). "Retinal ICAM-1 mRNA was increased in diabetes compared to control, but was not increased in diabetic rats fed the DHA-rich diet, highlighting the important role of ASM in diabetes-induced retinopathy." (PMID 23383097, 2013). "Our study demonstrated that serum levels of VEGF and ICAM-1 increased significantly as the level of retinopathy increased from diabetes with no retinopathy to proliferative retinopathy (p<0.001)." (PMID 23922493, 2013). "Previous work has shown that diabetes-induced increases in oxidative stress, upregulation of VEGF and ICAM-1 expression, vascular permeability increases and leukostasis are all associated with peroxynitrite formation as shown by increases in immunoreactivity for its biomarker nitrotyrosine." (PMID 24358357, 2013). "Although signaling pathways within endothelial cells obviously might increase endothelial expression of ICAM-1, we present evidence that marrow-derived cells contribute to the ICAM-1 upregulation on endothelial cells in diabetes." (PMID 23874797, 2013). "Furthermore, macrophage infiltration was found to be blocked by anti-ICAM-1 antibody, confirming that ICAM-1 mediates macrophage infiltration into diabetic kidney." (PMID 21663638, 2011). "Similar to the age-related gene expression changes, both Edn2 and Icam1 showed significantly higher expression in rats with diabetes compared to nondiabetic controls." (PMID 21633715, 2011). "This diabetes-induced ICAM-1 expression in ApoE−/− mice was not accompanied by increased levels of pro-inflammatory cytokines in retina, nor with elevated sVCAM levels, suggesting a different scenario than that found in diabetic wt mice." (PMID 20856927, 2010). "Furthermore, in diabetes, there is an upregulation of other adhesion molecules on endothelial cells, such as vascular cell adhesion molecule-1 (VCAM-1), intercellular adhesion molecule-1 (ICAM-1), and E-selectin." (PMID 39064844, 2024). "However, there were significant differences between the various subgroups concerning the age at onset of diabetes and the sP-selectin levels but not ICAM-1 and sVCAM-1." (PMID 39768295, 2024). "AM was not a predictor, while b-FG, VCAM-1 and ICAM-1 could be predictors for peripheral blood flow in diabetic PVD." (PMID 25287126, 2014). "Deletion of AR also inhibited the diabetes-induced increase in expression of iNOS but not ICAM-1, which is interesting because both are regulated by NF-κB, and both have been shown to be strongly related to the capillary degeneration occurring in retinas of diabetic animals." (PMID 23614016, 2013).
diabetes (continued). "Blocking the adhesion molecule, ICAM-1 or CD18, with specific antibodies in the present studies inhibited the leukocyte-mediated death of HRECs, and deletion of these proteins from diabetic mice previously inhibited the diabetes-induced degeneration of retinal capillaries in vivo." (PMID 24146542, 2013). "The role of ICAM1 in the development of diabetes and DN has not been fully explored." (PMID 23346076, 2012). "The concept that sRAGE levels may be elevated in response to serum AGE levels and reflect tissue RAGE expression in diabetes is supported by similar elevations in levels of ICAM-1 and VCAM-1 under the same circumstances since RAGE belongs to the same immunoglobulin superfamily as ICAM-1 and VCAM-1." (PMID 27434539, 2016). "Diabetes results in a marked increase in the expression of ICAM-1, VEGF, and TNF-α, whereas MALAT1 knockdown could significantly reduce the induction of VEGF, TNF-α, and ICAM-1, suggesting that MALAT1 knockdown could alleviate retinal inflammation in diabetic rats." (PMID 25356875, 2014). "However, when mRNA levels of VCAM-1, ICAM-1 and E-selectin were studied in isolated retinal vessels from ApoE−/− using the same assays as for intact retina, a clear increase of ICAM-1 in response to diabetes was observed (p<0.05) and similar trends were seen for VCAM-1 and E-selectin (n.s.)." (PMID 20856927, 2010). "Diabetes significantly increased the retinal expression of phospho-ERK1/2, HMGB1, VCAM-1, and ICAM-1 in comparison with the retinal levels in nondiabetic control rats." (PMID 39851513, 2025). "In this study, markers of endothelial dysfunction such as the ratios of VEGF/sVEGF, ICAM-1 and VCAM-1 were increased in patients with FTD and diabetes in comparison with those of patients without DM." (PMID 39202319, 2024). "In contrast to previous observation, the present study revealed that there was no significant recovery of diabetes corresponding to TNF-α and ICAM-1 in serum and tears." (PMID 39279894, 2024). "Neither the expression of the ICAM-1, TNFα, nor MCP-1 was affected by either diabetes or Cmpd17b treatment." (PMID 32085666, 2020). "The rise of ICAM-1 and VCAM-1 in vasculopathy and their negative correlation with A/BI support the role of inflammation in pathogenesis of diabetic PVD and indicates that inflammation could be the cause of reduced vascular integrity and contribute to vascular complications in diabetes." (PMID 25287126, 2014). "As well, pioglitazonereduces the levels of ICAM-1 and VCAM-1 in obese patients without diabetes, without affecting soluble E-selectin levels." (PMID 19107216, 2008). "In contrast, the chemokine RANTES or the adhesion molecules ICAM-1 and VCAM-1 were not transcriptionally regulated in the kidney in response to hypertension or diabetes." (PMID 15918915, 2005). "Pro-inflammatory molecules such as VEGF, ICAM-1, MCP-1, IL-6, IL-8, and TNF were consistently detected at higher levels in the vitreous of diabetic patients compared to those without diabetes, and in PDR or diabetic macular edema (DME) patients compared to non-DR patients." (PMID 35802672, 2022). "Western blot analysis of homogenized retinal tissue revealed that diabetes significantly increased the protein levels of phospho-ERK1/2, the p65 subunit of NF-κB, ICAM-1, and VEGF at 2 weeks after the induction of diabetes when compared with the retinas of non-diabetic control rats." (PMID 35082694, 2021). "Therefore, diabetes-induced changes in PAR-1 and ICAM-1 expression were studied in animals specifically lacking CAPN1 in platelets." (PMID 33258989, 2020). "Already after 4 weeks of diabetes, a time-point when no changes in aortic plaque size had yet occurred, expression of VCAM-1, MCP-1, IL-1β, Cox2, TF and maybe also IL-6 and ICAM-1 (borderline significance) were higher than in control non-diabetic mice." (PMID 23755169, 2014).